CDRT15L2 (CMT1A duplicated region transcript 15 like 2)
Tractability: Antibody: UniProt predicts a signal peptide or a membrane-spanning region.
Gene: Protein-coding gene on chromosome 17 (20,579,724 to 20,580,911, forward strand). Ensembl gene ENSG00000214819.
Subcellular location: Membrane
Gene Ontology:
Cellular component: membrane
Genetic constraint (gnomAD): Loss-of-function variants: 12 observed, 16.56 expected, observed/expected ratio (o/e) 0.72, 90% interval 0.46 to 1.17. The upper end of that interval is the gene's LOEUF score, 1.17, which puts it in group 5 of 6, group 1 being the genes least tolerant of losing a copy. Missense variants: 262 observed, 262.66 expected, observed/expected ratio (o/e) 1, 90% interval 0.9 to 1.11. Synonymous variants: 112 observed, 107.58 expected, observed/expected ratio (o/e) 1.04, 90% interval 0.89 to 1.22.
Homologues: Orthologues: macaque CDRT15 (54% identical). Paralogues in human: CDRT15 (53% identical).